ENSG00000212624
Synonyms: LOC124900447
Gene: Small nucleolar RNA gene on chromosome 1 (51,724,775 to 51,724,896, reverse strand). Ensembl gene ENSG00000212624.
Gene Ontology:
Biological process: RNA processing
Cellular component: nucleolus
Homologues: Orthologues: mouse Gm24233 (85% identical), rat Snora26l1 (83% identical), rat LOC120102084 (62% identical). Paralogues in human: SNORA26 (92% identical).